CD1D (CD1d molecule)
Diseases named in the same sentence as CD1D in open-access papers (continued):
Sharing a sentence is not in itself a finding about the gene and the disease.
liver fibrosis (5 papers, 2020 to 2023). "In TAA-induced liver fibrosis, the CD1d deficient mice show ameliorated liver fibrogenesis with blunted TIMP-1 expression, whereas in CCl4-induced liver fibrosis, NKT-deficient mice are more susceptible." (PMID 32676074, 2020). "In the present study, FFD-induced hepatic fibrosis was comparable in WT mice and CD1d-deficient mice, while the MCD diet induced a higher degree of fibrotic response in CD1d-/- mice than WT mice, which suggested that NKT cells play a role in inhibiting liver fibrogenesis in the MCD model." (PMID 35950602, 2022). "However, NASH and liver fibrosis were ameliorated in the liver of CD1d-deficient mice fed with high-fat high-carbohydrate diet, suggesting that CD1d-dependent NKT cells were profibrotic in NASH." (PMID 32708044, 2020). "The MCD diet induced a higher degree of NASH and a more advanced stage of liver fibrosis than FFD in either WT or CD1d-/- mice." (PMID 35950602, 2022). "Male Balb/c mice exhibited NKT-cell protection against steatohepatitis whereas CD1d−/− males on HFCD presented decreased hepatoprotection, increased liver fibrosis, inflammation, neutrophilic infiltration, and inflammatory macrophages." (PMID 37964320, 2023). "Liver fibrosis was attenuated in CD1d-/- mice that lacked NKT cells." (PMID 35950602, 2022).
malaria (5 papers, 2011 to 2025). Malaria is a serious and sometimes fatal disease caused by a parasite that commonly infects a certain type of mosquito which feeds on humans. "A systematic study performed in the context of malaria infection reported that CD1d-restricted natural killer T (NKT) cells can contribute to either protection against or susceptibility to malaria depending on the host genetic background." (PMID 37964320, 2023). "Finally, we used human CD1D tetramers to characterize the ex vivo frequencies and phenotypes of iNKT cells in peripheral blood and tissues of 12 rhesus macaques that had undergone necropsy after malaria challenge or BCG vaccination." (PMID 31123763, 2019). "This process requires both NKT cell activation and CD1d molecules, as well as the production of IFN-γ, demonstrating the complex interplay between innate and adaptive immune components in malaria." (PMID 39861032, 2025). "Based on the B cell numbers per spleen, we concluded that CD1d-restricted and I-Ab-restricted CD4+ T cells contribute to the expansion of the spleen B cell population during early P. chabaudi malaria." (PMID 21814579, 2011). "Likewise, in P. yoelii malaria, the absence of CD1d-restricted CD4+ T cells leads to increased parasitaemias in the 4th week of infection but not earlier, while the acquisition of protective immunity is not affected." (PMID 21814579, 2011).
Crohn disease (4 papers, 2018 to 2024). A gastrointestinal disorder characterized by chronic inflammation involving all layers of the intestinal wall, noncaseating granulomas affecting the intestinal wall and regional lymph nodes, and transmural fibrosis. "The first identification of CD1b/c “patch” implies the presence of any other motifs for known biased TCR Vβ genes, such as TRBV7-9+ T cells restricted by human CD1c or CD1d, which are associated with Crohn’s disease." (PMID 39718834, 2024). "In patients with ulcerative colitis (UC), sulfatide-reactive CD1d-restricted type II NKT cells in lamina propria mononuclear cells are increased compared to healthy controls and patients with Crohn’s disease." (PMID 29599785, 2018). "Moreover, sulfatide stimulation induced pathogenic interleukin (IL)-13 production and IL-13Rα2 expression on CD1d-restricted type II NKT cells from UC patients but not from healthy controls or patients with Crohn’s disease." (PMID 29599785, 2018). "We first compared differential gene expression of two class Ib MHC molecules (HLA-E and CD1d) and one class Ia MHC molecule (HLA-A) between non-inflamed and inflamed colon from descending and ascending colon in refractory Crohn’s disease (CD) using the CERTIFI cohort (GSE100833)." (PMID 34911745, 2021).
HIV-1 infection (4 papers, 2011 to 2025). The type species of lentivirus and the etiologic agent of acquired immunodeficiency syndrome (AIDS). "Interestingly, in GFP-HIV-1 Nef deficient infections, there was minimal CD1d downregulation thus indicating that the immunomodulation of CD1d expression in HIV-1 infection is Nef-dependent." (PMID 39355244, 2024). "We found that HIV-1 infection induced the downregulation of CD1c and CD1d expression through a Vpu-dependent, Nef-independent mechanism, and the concomitant HIV-1-induced production of host cholesterol decreased the extent of CD1c and CD1d modulation." (PMID 23347583, 2013). "In addition to the finding that CD4+ type I NKT cells are also permissive to HIV-1 infection, it has also been shown that HIV-1 infection can interfere with CD1d expression and thus, CD1d-dependent activation of type I NKT cells." (PMID 39355244, 2024). "HIV-1 infection induces the production of cholesterol, which may be presented by CD1c/CD1d molecules to initiate an immune response." (PMID 23347583, 2013). "We found Tat-induced methylation variations in genes such as TNF, CD1C, and CD1D, belonging to pathways involved in the binding, processing, and presentation of lipid antigens, immune response, and inflammatory pathways, which are processes well-documented during HIV-1 infection." (PMID 40103825, 2025).
myeloid leukemia (4 papers, 2019 to 2022). A clonal proliferation of myeloid cells and their precursors in the bone marrow, peripheral blood, and spleen. "In myeloid leukemia patients, for instance, purified PBMCs-derived iNKT cells are responsive to stimulation with α-GalCer/CD1d-tetramer with production of IFN-γ, TNF-α, IL-2, and IL-4 and cytotoxic against autologous leukemic cells, that are CD1d+." (PMID 35757002, 2022).
nephritis (4 papers, 2013 to 2022). Inflammation of renal tissue. "Moreover, glycosphingolipid biosynthesis played an important role in nephritis development and CD1d-mediated lipid antigen presentation." (PMID 28486945, 2017). "Thus, it is reasonable to suggest that the protective effects of β2m against humoral autoimmunity and nephritis may be mediated, at least in part, via the regulatory effect of CD1d-reactive NKT-cells." (PMID 23531237, 2013). "Similarly, the adoptive transfer of Bregs (CD1d + CD5 + B cells) into CD19 − / − NZB/W F1 mice restored splenic Tregs and delayed the development of nephritis." (PMID 36510250, 2022). "All, but one, of these effects of β2m-deficiency may be explained, at least in part, by the absence of CD1d, with which β2m non-covalently associates, as CD1d° BWF1 mice also have accelerated nephritis, increased IgG anti-DNA antibody and RF, but reduced anti-phospholipid antibody levels." (PMID 23531237, 2013).
prostate tumor (4 papers, 2010 to 2018). "By utilizing the same TRAMP prostate cancer model as a source of primary prostate tumors, we demonstrated that CD1d-expressing prostate tumor cells can directly activate iNKT cells, but biased them toward making Th2 cytokines." (PMID 29559971, 2018). "For instance, prostate tumor cells by expressing CD1d molecules inhibit the activation of IFNy secretion by type-I NKT cells." (PMID 24212972, 2011). "The tumor cell line TRAMP-C2, human prostate tumor cell lines as well as mouse prostate epithelium (PrEC) expressed CD1d molecules on the surface, suggesting prostate (tumor) cells can directly interact with iNKT cells." (PMID 24212972, 2011). "Prostate tumor cells expressing CD1d partially activated iNKT cells, as appreciated by up-regulation of CD25, PD-1 and the IL-12R." (PMID 20593019, 2010). "Both primary prostate tumors as well as mouse and human CaP cell lines express high levels of CD1d, permitting direct interaction with iNKT cells." (PMID 20593019, 2010). "One may speculate that CD1d expressing prostate tumor cells present an Th2-biasing endogenous lipid antigen in CD1d molecules, explaining the basal production of cytokines in the absence of exogenous α-GC." (PMID 24212972, 2011). "Recent studies performed in the murine prostate TRAMP model demonstrated that CD1d-positive TRAMP prostate tumor cells could induce cytokine defects in tumor-infiltrating DN iNKT cells." (PMID 21695190, 2011). "Whether the CD1d expression on prostate tumor cells is functional and can activate iNKT cells was tested using the iNKT cell hybridoma DN32." (PMID 20593019, 2010). "However, despite inducing up-regulation of these activation markers and, hence, delivering positive signals, prostate tumor cells inhibited the IL-12-induced STAT4 phosphorylation in a cell-cell contact dependent but CD1d-independent manner." (PMID 20593019, 2010). "Thus, it is conceivable that prostate tumor cells, in addition to CD1d-mediated signals activating iNKT cells deliver additional signals that block the translation or export of IFNγ in iNKT." (PMID 20593019, 2010). "When we directly tested the ability of iNKT cells to respond to CD1d-expressing prostate tumor cells from TRAMP mice in vitro, we found that they did not elicit a Th1 phenotype that would be indicative of killing." (PMID 29559971, 2018).
type 1 diabetes (4 papers, 2009 to 2024). "The TSP prediction rule to diagnose Type I Diabetes is based on the relative expression of the genes CD1D and PSD." (PMID 19961616, 2009).
Acute hepatitis (3 papers, 2012 to 2020). Acute hepatic injury resulting from inflammation typically accompanied by increased serum alanine transaminase activity. "In mice, acute hepatitis can be induced by concanavalin A (ConA) treatment, which causes rapid activation of CD1d-positive natural killer (NK) T cells." (PMID 22347449, 2012). "In view of this, it is interesting to note that in a transgenic HBV transfer mouse model, induction of acute hepatitis was mediated by CD1D-restricted NKT cells." (PMID 32012176, 2020).
dyslipidemia (3 papers, 2011 to 2018). "Thus, CD1d-restricted, type II NKT cells may be a novel target for therapeutic intervention in the metabolic syndrome." (PMID 22383967, 2012).
Fabry disease (3 papers, 2019 to 2024). Fabry disease (FD) is a progressive, inherited, multisystemic lysosomal storage disease characterized by specific neurological, cutaneous, renal, cardiovascular, cochleo-vestibular and cerebrovascular manifestations. "Deficiency of this enzyme in Fabry disease causes aberrant accumulation of lipid antigens and activation of immature CD1d-restricted natural killer T (NKT) cells, resulting in autoimmunity." (PMID 36794069, 2023). "Moreover, studies observed an increase in blood lymphocyte counts, with notable elevations in specific T cytotoxic cell subsets (CCR4+CXCR3+ and CCR6+), as well as the presence of MHCII+ CD1d+ CD11b+ CD31+ monocytes in patients with Fabry disease." (PMID 39596318, 2024). "Lipid antigen presentation by CD1d is impaired in mouse models of several LSD including Sandhoff, Niemann-Pick C (NPC), GM1 gangliosidosis, and Fabry disease." (PMID 31214199, 2019). "Hence, both in Fabry disease and MPS substrate accumulation is considered to trigger TLR4 and CD1d systems contributing to irreversible organ damage." (PMID 36794069, 2023). "Furthermore, patients with Fabry disease exhibit elevated blood lymphocyte counts, increased levels of specific T cytotoxic cell subsets (CCR4+CXCR3+ and CCR6+), higher numbers of MHCII+ CD1d+ CD11b+ CD31+ monocytes, and notable tissue infiltration by macrophages and B cells." (PMID 39596318, 2024).
fibrosarcoma (3 papers, 2011 to 2018). A malignant mesenchymal fibroblastic neoplasm affecting the soft tissue and bone. "Yet again, this protective effect was evident only when the recipient mice expressed CD1d, perhaps implying that the fibrosarcoma cells expressed lipids capable of activating iNKT cells when presented by CD1d." (PMID 29973936, 2018).
Gaucher disease (3 papers, 2015 to 2021). Gaucher disease (GD) is a lysosomal storage disorder encompassing three main forms (types 1, 2 and 3), a fetal form and a variant with cardiac involvement (Gaucher disease - ophthalmoplegia - cardiovascular calcification or Gaucher-like disease). "Similarly, freshly isolated monocytes from Fabry and Gaucher disease patients had a normal ability to present α-Galactosylceramide (α-GalCer) antigen by CD1d." (PMID 31214199, 2019). "In PBMC of healthy individuals, approximately 0.5% of CD3+ lymphocytes stained with β-GlcCer/CD1d tetramers, similar to numbers in Gaucher’s disease patients, whereas 1–2% of CD3+ lymphocytes in these patients stained positive with β-GlcSph/CD1d tetramers, compared to 0.2% in healthy individuals." (PMID 26284062, 2015). "In Gaucher disease, gammopathies have been related to the development of clonal anti-lyso-glucosylceramide (LGL1) antibodies due to the activation of LGL1-specific CD1d-restricted invariant natural killer T cells (iNKTs)." (PMID 34768550, 2021).
hepatocellular carcinoma (3 papers, 2021 to 2025). A malignant tumor that arises from hepatocytes. "Within this class, cardiolipin (CL), overexpressed early in hepatocellular carcinoma (HCC) in mice, is released during mitochondrial degradation and is associated with CD1d lipid presentation to iNKT and γδ T cells, promoting tumor growth by supporting mitochondrial function." (PMID 40746558, 2025).
herpesvirus infection (3 papers, 2006 to 2015). "Studies in HSV-1 murine models support a role for iNKT cells in controlling herpesvirus infection: CD1d- and Jα18-deficient mice infected with HSV-1 experience higher viral loads and morbidity compared to wild-type littermates." (PMID 26161082, 2015). "We highlight the role of iNKT cells in herpesvirus infections and the significance of CD1d expression in controlling herpesvirus replication." (PMID 26161082, 2015). "Supporting this assumption are several lines of evidence showing that CD1d is required to activate iNKT cells following human herpesvirus infection." (PMID 26161082, 2015). "Natural killer T (NKT) cells are a unique group of CD1d-restricted innate-like lymphocytes and patients deficient in NKT cells develop severe and fatal herpesvirus infections." (PMID 26161082, 2015). "Significant progress over the last decade has greatly improved our understanding of iNKT cell biology but the precise nature of the CD1d-restricted antigens that activate iNKT cells in herpesvirus infections is still unknown." (PMID 26161082, 2015). "Effect of human herpesvirus infection on CD1d expression and iNKT cells." (PMID 26161082, 2015). "Moreover, hepatitis B infection has been shown to induce the expression of endogenous lipid antigens (lysophospholipids) in human and mouse hepatocytes, suggesting that herpesvirus infection may trigger the presentation of analogous self-lipids on CD1d." (PMID 26161082, 2015). "Thus, future work focused on accurately quantifying the expression of CD1d during herpesvirus infection may yield important insights into the kinetics of iNKT cell recognition and lead to the identification of the lipid antigens(s) that are possibly triggered by herpesvirus infections." (PMID 26161082, 2015).
hyperlipidemia (3 papers, 2018 to 2024). "It is known that hyperlipidemia is present in both mammary tissue and sera of BC patients, thus we investigated whether conditioned medium from BC cells inhibited CD1d-mediated NKT cell activation." (PMID 39596374, 2024).
invasive breast carcinoma (3 papers, 2011 to 2019). A carcinoma that infiltrates the breast parenchyma. "We provide the first evidence that expression of CD1d in human mammary epithelial cells is lost in the transition from normal to invasive breast cancer." (PMID 21695190, 2011).
mantle cell lymphoma (3 papers, 2015 to 2023). Mantle cell lymphoma is a rare form of malignant non-Hodgkin lymphoma affecting B lymphocytes in the lymph nodes in a region called the ``mantle zone''. "Moreover, Tiper and Webb also demonstrated that Trichostatin-A, a pan-HDACi enhanced both CD1d- and MHC class II-mediated antigen presentation in mantle cell lymphoma (MCL), as well as inhibiting STAT3-regulated inflammatory cytokine secretion by MCL cells." (PMID 37808081, 2023).
myocarditis (3 papers, 2015 to 2020). Myocarditis is a condition that is characterized by inflammation of the heart muscle (myocardium). "It has been reported that CD1d was upregulated on cardiomyocytes during inflammatory conditions like myocarditis and coxsakievirus B3 infections." (PMID 28855904, 2017). "In mice, development of myocarditis following infection with coxsackievirus B3 (CVB3) relied on CD1d up-regulation and CD1d-dependent activation of Vγ4+ γδ T cells." (PMID 26284062, 2015). "Myocarditis in BALB/c was shown to be mediated by CD1D-restricted immune response." (PMID 32012176, 2020).
non-small cell lung carcinoma (3 papers, 2013 to 2023). A group of at least three distinct histological types of lung cancer, including non-small cell squamous cell carcinoma, adenocarcinoma, and large cell carcinoma. "In a human study, the prognosis of human non-small cell lung cancer (NSCLC), correlated with the expression of CD1d on lung tissue and the induction of CD1d on the NSCLC cell line in vitro, up-regulated the iNKT cell-mediated tumor cell elimination." (PMID 36769513, 2023).
pancreatic cancer (3 papers, 2018 to 2025). "By using a mouse model of oncogene-induced pancreatic cancer, iNKT cells have been shown to have a preferential activity on M2-like macrophages, which are increased in CD1d−/− pancreatic cancers." (PMID 30369933, 2018). "Notably, PDAC patients exhibited heightened infiltration of myeloid-derived suppressor cells (MDSCs), which express CD1d, within pancreatic tumors." (PMID 40231459, 2025).
parasitemia (3 papers, 2018 to 2022). "Here we show that CD1d deficient mice display higher peak parasitemia but have no defect in parasite-specific Ab production or evidence of CD1d-restricted T cells assuming a Tfh cell phenotype." (PMID 30374346, 2018). "The population of IL-10 producing B220+CD5+CD1d+ cells was found to be directly correlated with the increase of parasitemia in both lethal and non-lethal strains of Plasmodium at early stage of infection." (PMID 35625397, 2022).
schistosomiasis (3 papers, 2015 to 2022). An infectious disease caused by parasitic trematodes of the genus Schistosoma that colonize human blood vessels and release eggs that can cause granulomatous reactions leading to acute (swimmer's itch or acute schistosomiasis syndrome) or chronic disease. "CD1d-deficient mice developed a markedly reduced Th2 response during schistosomiasis indicating an important role of CD1d-restricted T cells in the development of a protective immune response." (PMID 26284062, 2015). "During murine schistosomiasis, NKT cells could recognize glycolipids presented by CD1d on APCs, inducing the production of type 2 cytokines (IL-4, IL-5, IL-13) and influence the Th1/Th2 balance of the immune response." (PMID 36618421, 2022).